OR1N2 (olfactory receptor family 1 subfamily N member 2)
Description:
Odorant receptor.
Synonyms: OR9-23
Tractability: Antibody: its Gene Ontology location is reachable by antibodies, with high confidence; UniProt predicts a signal peptide or a membrane-spanning region.
Gene: Protein-coding gene on chromosome 9 (122,553,112 to 122,554,214, forward strand). Ensembl gene ENSG00000171501.
Subcellular location: Membrane
Pathways (Reactome):
Sensory Perception: Expression and translocation of olfactory receptors; Olfactory Signaling Pathway
Gene Ontology:
Molecular function: olfactory receptor activity; G protein-coupled receptor activity
Biological process: signal transduction; detection of chemical stimulus involved in sensory perception of smell; G protein-coupled receptor signaling pathway
Cellular component: plasma membrane; membrane
Genetic constraint (gnomAD): Loss-of-function variants: 1 observed, 0.43 expected, observed/expected ratio (o/e) 2.33. That is too few expected variants to judge how well the gene tolerates losing a copy. Missense variants: 358 observed, 398.66 expected, observed/expected ratio (o/e) 0.9, 90% interval 0.82 to 0.98. Synonymous variants: 152 observed, 157.13 expected, observed/expected ratio (o/e) 0.97, 90% interval 0.85 to 1.11.
Homologues: Orthologues: chimpanzee OR1N2 (98% identical), mouse Or1n2 (88% identical), rat Or1n2 (87% identical), dog OR1F15 (58% identical). Paralogues in human: OR1N1 (57% identical), OR1E1 (55% identical), OR1F1 (55% identical), OR1E2 (54% identical), OR1I1 (53% identical), OR7C1 (53% identical), OR7D4 (53% identical), OR1J4 (53% identical), OR7C2 (53% identical), OR1L4 (53% identical), OR1L6 (53% identical), OR1S1 (53% identical), and 116 more.